CD109 (CD109 molecule)
Diseases named in the same sentence as CD109 in open-access papers (continued):
Sharing a sentence is not in itself a finding about the gene and the disease.
osteosarcoma (1 paper, 2024). A usually aggressive malignant bone-forming mesenchymal neoplasm, predominantly affecting adolescents and young adults. "While CD109’s role in TGF-β signaling appears limited in osteosarcoma, its involvement in BMP signaling highlights a distinct mechanism in this cancer." (PMID 39990858, 2024). "Given its established connections to inflammatory processes in bone and its modulation of BMP signaling, CD109’s role in inflammation within the osteosarcoma tumor microenvironment warrants further investigation." (PMID 39990858, 2024). "CD109 is highly expressed in osteosarcoma, promote tumor cell migration via suppression of bone morphogenetic protein-2 (BMP-2)-induced Smad1/5/9 phosphorylation, where its expression correlates with poor prognosis." (PMID 39990858, 2024). "This hypothesis strengthens the argument for studying CD109 as a potential link between inflammation, bone remodeling, and cancer progression in osteosarcoma." (PMID 39990858, 2024).
pancreatic adenocarcinoma (1 paper, 2018). "A substantial difference in CD109 expression in pancreatic adenocarcinoma compared to normal pancreatic tissue was also observed and no staining was seen in other pancreatic tissue components such as blood vessels, pancreatic acini, stromal fibrous tissue, adipose tissue and inflammatory cells." (PMID 29731998, 2018).
papilloma (1 paper, 2016). A benign epithelial neoplasm that projects above the surrounding epithelial surface and consists of villous or arborescent outgrowths of fibrovascular stroma. "This difference suggests that CD109 deficiency suppresses DMBA/TPA-induced epidermal hyperplasia or papilloma formation by a mechanism different from those operating under physiological conditions as observed in our previous study." (PMID 27756876, 2016). "The number of Ki-67-positive cells was significantly higher in papillomas of CD109+/+ mice than in those of CD109−/− mice at 17 weeks after DMBA initiation (P < 0.05)." (PMID 27756876, 2016). "The results show that there were no apparent changes in the levels of TGF-β1 expression or Smad2 phosphorylation between CD109+/+ and CD109−/− papillomas." (PMID 27756876, 2016). "Additionally, the finding that Smad2 phosphorylation levels were similar between CD109+/+ and CD109−/− papillomas could result from the lower amount of stroma found in papillomas compared with in normal skin." (PMID 27756876, 2016). "In conclusion, our findings suggest that CD109 deficiency plays a role in suppression of the mutation rate of the H-ras gene in the early phase of DMBA/TPA-induced skin tumorigenesis by enhancing the TGF-β/p21/Nrf2 pathway, and significantly reduces the number and size of papillomas." (PMID 27756876, 2016). "We next compared the histological changes in dorsal skin before papilloma formation between CD109+/+ and CD109−/− mice." (PMID 27756876, 2016). "There were no apparent histological differences between CD109+/+ and CD109−/− papillomas, except for the tumor size." (PMID 27756876, 2016).
periodontitis (1 paper, 2024). An acute or chronic inflammatory process that affects the tissues that surround and support the teeth. "This suggests that it is necessary to regulate the CD109 expression through controlling the force during orthodontic clinical treatment, especially when treating adult patients and patients with periodontitis, who show a deterioration in the regenerative capacity of periodontal tissues." (PMID 38885217, 2024).
platelet disorders (1 paper, 2024). "Elevated CD109 expression has been linked to various conditions, including skin diseases, platelet disorders, and cancers, all of which have a significant immune component." (PMID 39990858, 2024).
prostate carcinoma (1 paper, 2023). A carcinoma that arises from epithelial cells of the prostate gland. "Recent studies have identified CD109 as a new marker for invasive breast and prostate carcinoma." (PMID 37476073, 2023). "We also identified a higher percentage of subclonal cell populations in aggressive taxane resistance prostate cancer subtypes overexpressing CD55 and CD109." (PMID 37476073, 2023).
psychotic disorder (1 paper, 2020). An abnormal condition of the mind that involves a loss of contact with reality. "CD109 was higher in the disease group in the plasma proteome comparison between the psychotic disorder and the normal group." (PMID 33126421, 2020).
skin cancer (1 paper, 2016). "Further investigation is necessary to clarify the role of CD109 in invasion, differentiation, and metastasis of skin cancer." (PMID 27756876, 2016).
skin squamous cell carcinoma (1 paper, 2019). A carcinoma arising from the squamous cells of the epidermis. "Consistent with this hypothesis, the release of CD109 by bone marrow mesenchymal stem cells has recently been shown to attenuate EMT in skin squamous cell carcinoma, and AMFR plays an important role in regulation of the anti-cancer immune Stimulator of interferon genes (STING) pathway." (PMID 30634628, 2019).
Skin tumors (1 paper, 2016). "Macroscopically, we found fewer and smaller skin tumors in CD109−/− mice compared with in CD109+/+ mice in this model." (PMID 27756876, 2016). "Skin tumors tended to appear later and tumor number per mouse was significantly lower in CD109−/− mice than in CD109+/+ mice (P < 0.05)." (PMID 27756876, 2016).
small cell lung carcinoma (1 paper, 2019). Small cell lung cancer (SCLC) is a highly aggressive malignant neoplasm, accounting for 10-15% of lung cancer cases, characterized byrapid growth, and early metastasis. "CD109 was found to be associated with the growth of small cell lung cancer, but this gene may be associated with the pathogenesis of EOC." (PMID 30970615, 2019).
vulvar squamous cell carcinoma (1 paper, 2018). An invasive squamous cell carcinoma arising from the vulva. "A positive correlation has been reported between CD109 expression and tumour grade in patients with vulvar squamous cell carcinoma." (PMID 29731998, 2018).
tumor (55 papers, 2007 to 2026). "Elevated CD109 expression was associated predominantly with unfavorable survival in several tumor types, whereas opposite prognostic associations were observed in a subset of cancers." (PMID 42067796, 2026). "Bioinformatic analysis revealed that high CD109 expression was associated with an immunosuppressive tumor immune microenvironment, characterized by the enrichment of M2-like tumor-associated macrophages (TAMs) and activation of oncogenic signaling axes." (PMID 42067796, 2026). "We identified KRASG12D PDAC derived CD109+ EVs that transmit circPNIT to foster tumor‐associated axonogenesis and PNI, both in vitro and in vivo." (PMID 39488792, 2024). "In this study, we elucidated for the first time that KRASG12D‐related PDAC cells exhibit severe PNI via the secretion of tumor‐derived CD109+ EVs, which deliver circPNIT to facilitate tumor‐associated axonogenesis and PNI." (PMID 39488792, 2024). "It is important to establish not only that CD109 plays a causal role in SCC tumor growth or metastasis but also to elucidate the molecular mechanisms by which CD109 regulates the oncogenic pathways such as EGFR signaling." (PMID 35954339, 2022). "In recent years, CD109 was also associated with different tumor entities and identified as a possible future diagnostic marker linked to reduced patient survival." (PMID 33738281, 2021). "TMSB4X and CD109 were also associated to tumor conditions, being as well able to discriminate PA from all other tumors." (PMID 33469081, 2021). "Of the other possible associations, a significant association was detected between CD109 expression and tumor grade (P = 0.0002)." (PMID 33986188, 2021). "Reduced expression of CD109 on tumor vessels was associated with large tumor size, microvascular invasion, and advanced tumor stage." (PMID 27121053, 2016). "The associations of CD109 expression in tumor vessels with clinicopathological characteristics were compared between the two groups." (PMID 27121053, 2016). "Previous studies focused more on CD109 expression on tumor cells and its associations with malignant behavior of tumor cells and patient prognosis." (PMID 27121053, 2016). "Further analyses using different types of tumorigenesis models such as ultraviolet radiation would provide insights into the mechanism of the tumor-suppressing effects of CD109 associated with chronic inflammation." (PMID 27756876, 2016). "In the xenografted mouse experiments, we investigated the association between tumor volume and concentration of tumor-secreted CD109 in the serum." (PMID 24400073, 2014). "Higher expression of CD109 was significantly associated with histologic grade, tumor stage, and distant metastases (p=0.021, 0.0012, and 0.0003 respectively)." (PMID 24376795, 2013). "In recent years, CD109 emerged as a tumor marker for different tumor entities and expression of CD109 could be linked to adverse outcome in patients." (PMID 38562713, 2024). "A possible mechanistic explanation for the paradox that CD109 loss promotes EMT, but forfeits tumorigenicity and metastatic ability in SCC cells is that the loss of CD109 action leads to an irreversible and tumor-suppressive EMT program which generates fully differentiated mesenchymal phenotype." (PMID 39990858, 2024). "By the end of the experiment (day 40), none of the mice injected with CD109KO cells (0/6) developed any tumors, whereas all mice injected with A431 cells formed tumors (6/6), indicating that the loss of CD109 eliminated xenograft tumor growth of A431 SCC cells in vivo." (PMID 35954339, 2022). "We then used in vitro tumor spheroid formation assays to determine whether, and how, the loss of CD109 affects cancer stem cell populations in SCC cells." (PMID 35954339, 2022). "Thus, it is possible that the loss of CD109 action leads to an irreversible and tumor-suppressive EMT program, as it generates a fully differentiated mesenchymal phenotype, resulting in the loss of tumorigenicity and metastatic ability." (PMID 35954339, 2022).
tumor (continued). "This TF directly regulates the E-to-C-associated gene CD109 in tumor edge-derived cells." (PMID 33392508, 2020). "The Janus face of TGF-β’s effect on different tumor development stages indicates that other intracellular mechanisms may crosstalk with CD109 in addition to its association with TGF-β signaling." (PMID 33375719, 2020). "Although the mechanisms underlying the development and progression of the corresponding human skin disease remain elusive, CD109 deficiency may be a factor in the tumor-suppressing effects of chronic skin inflammation." (PMID 27756876, 2016). "We previously reported that CD109 is associated with human tumor development, especially in SCCs." (PMID 27756876, 2016). "Moreover, multivariate analysis showed that low CD109 expression on tumor vessels was an independent risk factor for disease-free survival (P = 0.001)." (PMID 27121053, 2016). "Our results show that the levels of CD109, IL6Rα, pSTAT3 and NRF2 are markedly upregulated in tumor sections compared to normal tissue and CD109 levels correlate significantly with those of IL6Rα/pSTAT3/NRF2." (PMID 40317079, 2025). "The elevated expression of CD109 was found to promote tumour metastasis and drug resistance in lung cancer via activation of EGFR-AKT-mTOR signalling pathways and aggressiveness of cervical squamous cell carcinoma with the EGFR regulation." (PMID 40227788, 2025). "CD109 is essential for tumor progression by regulating EGFR/Akt signaling, usually involved in inflammation-related pathways." (PMID 39990858, 2024). "Taken together, these results indicate that KRASG12D PDAC‐derived CD109+EV promote PNI in KRASG12D mutant tumor tissues by transferring circPNIT." (PMID 39488792, 2024). "CD109 overexpression correlates with poor prognosis and promotes tumor cell migration via suppression of BMP-2-induced Smad1/5/9 phosphorylation." (PMID 39990858, 2024). "In contrast, tumor growth was markedly reduced due to PTX treatment in mice injected with sh-CD109 cells." (PMID 37373457, 2023). "CD109, which is expressed on the cell surface of various malignant tumors, is involved in promoting tumor initiation, growth, and metastasis and is related to poor prognosis." (PMID 37373457, 2023). "Using a xenograft mouse model, it was confirmed that PTX administration in xenografts of CD109-silenced A2780-R cells significantly attenuated in vivo tumor growth." (PMID 37373457, 2023). "CD109 is known to induce tumor malignancy and poor prognosis through transforming growth factor beta (TGF-β) signal activation." (PMID 37373457, 2023). "In summary, our studies show that CD109 is required for subcutaneous tumor formation and lung colonization of vulvar SCC cells." (PMID 35954339, 2022). "This highlights CD109, a glycosylphosphatidylinositol (GPI)-anchored protein, which was recently reported its association with different tumor entities and a possible future diagnostic marker linked to reduced patient survival." (PMID 36299526, 2022). "The role of CD109 in tumor progression and metastasis was studied using xenograft tumor growth and metastatic models." (PMID 35954339, 2022). "Both the primary tumor lesion and the metastatic lymph node were positive for CD109 protein in all seven cases, while the normal squamous epithelium was almost negative." (PMID 33565282, 2021). "CD109 was highly expressed in invasive tumor nests and in malignant cells surrounding the keratinized region." (PMID 33565282, 2021). "We also studied the role played by the tumor stroma, especially the microglial cells, by costaining of CD109 and ionized calcium-binding adapter molecule 1 (IBA-1) antibodies." (PMID 33986188, 2021). "Evaluation of the immunostaining revealed that CD109 is located at the plasma membrane of tumor cells in nearly all specimens (92.5%)." (PMID 33986188, 2021).
tumor (continued). "Bastola and colleagues demonstrated that CSCs were enriched at tumor edge compared to tumor core sites of GBM tissues and that the cells at core sites released soluble CD109 to induce CSCs at tumor edge to proliferate and to display radioresistance." (PMID 35006395, 2021). "CD109 silencing significantly reduced tumor size and decreased the number of satellite tumors and invading single cells compared with the control tumors." (PMID 33986188, 2021). "Costaining of the tumor blood vessels with type IV collagen revealed a significant increase in the collagen IV–positive “empty sleeves” devoid of endothelial marker in the CD109-silenced xenografts compared with controls." (PMID 33986188, 2021). "Further characterization of the CD109-silenced MES-like xenografts revealed a significant reduction in the number of Ki-67–positive proliferating tumor cells and OLIG2-positive GSCs." (PMID 33986188, 2021). "ANG2 promotes endothelial destabilization due to its potent repulsive signals to pericytes, which led us to investigate the pericyte distribution in tumor blood vessels in the control and CD109-silenced BT12 xenografts." (PMID 33986188, 2021). "EZR-negative tumor cells also show the significant upregulation of CD109, ID4, ST8SIA1, and NR4A1 genes." (PMID 32679794, 2020). "Mammalian studies have shown that CD109 is an oncogenic driver of tumor initiation and radioresistance in GBM." (PMID 32457905, 2020). "Further, CD109 was shown to act upstream of the YAP/TAZ signaling pathway and contribute to the stem cell and tumor-promoting properties of CD109-positive tumor cells." (PMID 32457905, 2020). "To further elucidate the molecular mechanisms of CD109-mediated tumor aggressiveness, we examined the involvement of YAP signaling." (PMID 33375719, 2020). "As expected, tumor core was enriched for CD109+ cells, while tumor edge contained more Olig2+ cells." (PMID 32938908, 2020). "Enforced expression of YAP rescued EMT gene expressions, and tumor migration and invasion in CD109-silenced cells." (PMID 33375719, 2020). "Validation using 52 human oral SCC tumor samples show that CD109 levels inversely correlate with tumor grade and the activation state of one such pathway, the TGF-β signaling pathway." (PMID 31695056, 2019). "Of the two mAbs, only KU42.33C was useful in determining the expression of CD109 in tumour cells by Western blot and immunohistochemistry." (PMID 29731998, 2018). "Further research is warranted and should aim to unravel the therapeutic potential of the humanised forms or conjugated versions of such antibodies in patients whose tumours overexpress CD109 antigen." (PMID 29731998, 2018). "Our findings suggest that CD109 inhibits TGF-β's tumor promoter function and supresses the malignant traits of cancer cells under the setting of our experimental conditions." (PMID 29221155, 2017). "The patients were divided into low (n = 95) or high (n = 47) CD109 expression groups according to expression levels in tumor vessels." (PMID 27121053, 2016). "In vitro and in vivo experiments using human umbilical vein endothelial cells (HUVEC) were performed to study the effects of different CD109 expression on tumor growth and metastasis." (PMID 27121053, 2016). "The correlation between CD109 expressed on tumor vessels and the prognosis after surgical resection of HCC was studied." (PMID 27121053, 2016). "The results indicated that the expression level of CD109 was higher in tumor spheres than that in 2D cultured NPC cells." (PMID 27419372, 2016). "Total tumor volume per mouse was also significantly lower in CD109−/− mice than in CD109+/+ mice (P < 0.05)." (PMID 27756876, 2016). "Patients with high CD109 expression on tumor vessels were older (P = 0.023), had smaller tumor size (P = 0.010), had less microvascular invasion (P = 0.036), and had earlier TNM stage (P = 0.015) than patients with low CD109 expression." (PMID 27121053, 2016).